CRP (C-reactive protein)
Diseases named in the same sentence as CRP in open-access papers (continued):
Sharing a sentence is not in itself a finding about the gene and the disease.
dengue (continued). "Among the 191 patients, the mean interval from dengue onset to blood sampling for CRP was 3.4 (±1.7) days and the mean CRP level was 19.3 (±27.6) mg/L." (PMID 26247033, 2015). "Of the 191 patients with dengue, 97 had CRP levels measured during their febrile phase, 85 during critical phase, and 9 during convalescent phase." (PMID 26247033, 2015). "Our analysis demonstrated that a CRP cutoff level of 30.1 mg/L had an excellent sensitivity (100%) for predicting DSS, whereas a CRP cutoff level of 24.2 mg/L had a sensitivity of 70% for severe dengue, during the first 3 days of illness (febrile phase)." (PMID 26247033, 2015). "The aim of our study was to evaluate the use of CRP levels in predicting severe illness of dengue at the early phase of infection." (PMID 26247033, 2015). "Lower WBC (2971 ± 1761/cmm vs. 3564 ± 1719/cmm, p = 0.006) and CRP level (6 ± 11 mg/L vs. 20 ± 24 mg/L, p = 0.011) and longer aPTT (39 ± 6 secs vs. 44 ± 10 secs, p = 0.021) were frequent to encounter in dengue-infected children." (PMID 24138072, 2013). "Whereas, the laboratory characteristics demonstrated significant differences of WBC (p = 0.006), CRP (p = 0.011) and aPTT (p = 0.021) between adult and pediatric dengue patients." (PMID 24138072, 2013). "According to several studies, CRP levels may be a useful biomarker for predicting the severity of dengue in adults." (PMID 40535371, 2025). "CRP levels are predominantly elevated among patients with severe dengue." (PMID 40109796, 2025). "Dengue and C-reactive protein (CRP) RDTs are commercially available and could be used for this purpose." (PMID 40340660, 2025). "This study highlights the predominance of DENV‐1 genotype I and the high proportion of secondary infections during the 2016 dengue outbreak in central Vietnam, with elevated high‐sensitive CRP levels indicating a heightened inflammatory response in secondary infections." (PMID 40838976, 2025). "A systematic review and meta-analysis identified key biomarkers predictive of severe dengue manifestations, including elevated levels of CRP, AST, IL-8, and decreased albumin levels for DHF, and increased levels of VCAM-1, syndecan-1, AST, and CRP for severe dengue (SD)." (PMID 40100920, 2025). "Notably, 43% of patients at presentation had normal C-reactive protein (CRP) levels: this finding should strengthen the clinical suspicion of dengue, as it is a common finding in arboviral infections." (PMID 40981333, 2025). "We aimed to evaluate the cost-effectiveness in Cambodia and Bangladesh of a putative, as-yet-undeveloped LF-RDT capable of diagnosing enteric fever and dengue, as well as measuring C-reactive protein (CRP) to guide antibiotic prescription, in primary care patients with acute NMFI." (PMID 38523864, 2024). "Whether IL-37 has a regulatory effect on CRP levels in dengue patient needs to be further investigated." (PMID 37024713, 2023). "The presence of mucocutaneous features and highly elevated CRP could distinguish MIS-C from dengue, while SLE has rarely been found in children during the COVID-19 pandemic." (PMID 38005840, 2023). "In this meta-analysis elevated serum CRP and AST levels in early disease (up to 96 h of fever) were associated with an increased risk of progression to either DHF (WHO 1997 classification) or severe dengue (WHO 2009 classification)." (PMID 37838744, 2023). "In our study, 8/9 (88.9%) severe dengue patients had more than 100 mg/L levels of CRP." (PMID 38235130, 2023). "Importantly, significantly higher levels of CRP, sVCAM-1 and sICAM-1 in the sera of severe than mild dengue patients (p<0.0001) suggest their role in disease severity." (PMID 38235130, 2023). "However, the status of CRP in severe secondary dengue remains unexplored in the population of eastern India." (PMID 33436908, 2021).
dengue (continued). "In addition, CRP was also reported as a predictor of shock in acute dengue and it was shown that those with dengue shock syndrome had median CRP values of 124.5 mg/L, which are values usually only seen in patients with acute bacterial infections." (PMID 33207759, 2020). "Likewise, an increase in serum CRP levels was found in dengue patients compared to healthy controls (p< 0.0001), which was more evident for DWWS and SD patients (p< 0.0001 and p< 0.05 respectively)." (PMID 30901375, 2019). "Moreover, a decrease in the expression of the inflammasome-related genes NLRP1, NLRC4, caspase-1, IL-1β and IL-18 was observed, as well as an increase in serum levels of C-reactive protein and IL-10 in dengue patients versus healthy donors." (PMID 30901375, 2019). "The mean CRP in the dengue subgroup was 19.77, with a median of 18.2 and IQR ranging from 5 to 27.1 whereas the OFI group had a much higher CRP with a mean of 105.50, median of 47.55, and an IQR ranging from 6.3 to 189 and a p value of 0.040, which achieved statistical significance." (PMID 29098002, 2017). "In addition, the level of hemoglobin, and C-reactive protein in dengue patients was significantly different from that in total non-dengue patients." (PMID 27240351, 2016). "In addition, the OFI group also showed higher white blood cell counts, platelet counts and C-reactive protein level than did the dengue group." (PMID 27240351, 2016). "Despite the limitations, this study is the first to examine the impact of single CRP testing on clinical decision-making and to evaluate the evidence base for the utility of this test to differentiate mild versus severe illness in adult patients with dengue." (PMID 26247033, 2015). "Notably, a significant association of higher CRP levels with DSS and severe dengue was found during the first 3 days of illness (febrile phase) in our series." (PMID 26247033, 2015). "The time from onset of dengue illness to CRP measured ranged from 1 to 5 days (median, 3 days)." (PMID 26247033, 2015). "CRP has also been assessed as a biomarker to discriminate between dengue and malaria." (PMID 26247033, 2015). "Similarly, a CRP level <50 mg/L helped to differentiate dengue fever from leptospirosis in New Caledonia." (PMID 24069477, 2013). "Other acute phase proteins that were elevated in dengue patients included C-reactive protein (CRP), alpha-2 macroglobulin (A2M) and ferritin (FT), while serum amyloid P (SAP), pro-calcitonin (PCT), tissue plasminogen activator (t-PA) and fibrinogen (FB) remained unchanged (not shown)." (PMID 23209847, 2012). "The study found a significant positive correlation between C-reactive protein and ferritin in dengue patients, suggesting that ferritin could serve as an additional biomarker, alongside CRP, for predicting hospitalization and assessing disease severity at an early stage of infection." (PMID 40692953, 2025). "The main finding was that this test should be able to diagnose enteric fever and dengue, at a minimum; there was also support for including C-reactive protein as a means of differentiating viral from non-viral causes of NMFI to guide empirical antibiotic prescribing." (PMID 38523864, 2024). "As adiponectin inversely correlated with CRP and was correlated with the extent of the rise in liver transaminases, it is likely that this adipokine in likely to reduce inflammation and possibly immunopathogenesis in dengue, which should be further investigated." (PMID 37676889, 2023). "The reason for elevation of CRP in complicated dengue patients could be manifold." (PMID 32454916, 2020). "Most importantly, we found that higher CRP levels and longer APTT were two independent risk factors, which might be useful for predicting concurrent bacteraemia in patients severely affected by dengue." (PMID 27902388, 2016).
dengue (continued). "The severity of liver injury was associated with higher levels of liver enzymes, inflammatory markers (CRP, PCT), and tissue damage markers (LDH, CK), underscoring the importance of closely monitoring liver function in dengue patients." (PMID 40692953, 2025). "ELISA is most widely used to measure biomarkers in blood, including C-reactive protein (CRP), which is a biomarker of inflammatory conditions including dengue." (PMID 40006981, 2025). "Severe dengue patients exhibited markedly elevated AST, ALT, alkaline phosphatase, bilirubin, and CRP levels, with a strong correlation between CRP and liver enzymes." (PMID 40692953, 2025). "This work studied the status of pentraxin (CRP/SAP) protein, ferritin, TNF-α and IL-1β levels in Dengue patients of different pathophysiological manifestations." (PMID 33436908, 2021). "Statistically significant increased CRP, SAP, ferritin, TNF-α and IL-1β titres were correlated in patients with severe clinical manifestations as compared to mild disease forms of dengue." (PMID 33436908, 2021). "Higher levels of CRP, SAP and Ferritin were observed in secondary cases compared to primary dengue cases which was statistically significant (p < 0.0001)." (PMID 33436908, 2021). "We assessed serum LPS, C-reactive protein (CRP), and procalcitonin in patients with acute dengue fever (DF = 129) and dengue haemorrhagic fever (DHF = 64) and correlated these observations with the presence of comorbid illnesses, and clinical disease severity." (PMID 33207759, 2020). "In addition to addressing the important question of whether CRP can be prognostically useful as a dengue biomarker, our findings add to the existing evidence base for its use in differentiating dengue from non-dengue causes of fever." (PMID 32063229, 2020). "Samples from 1120 patients with laboratory-confirmed dengue and 400 patients with OFI were tested with CRP." (PMID 32063229, 2020). "Other febrile diseases with intrinsic features of cytopenia and normal CRP included SFTS, drug fever, heat stroke, dengue, acute viral hepatitis, vivax malaria and acute HIV infection." (PMID 32134948, 2020). "The authors developed a model to measure the impact and cost-effectiveness of testing for elevated C-reactive protein (CRP), compared with RDTs for dengue and scrub typhus in the management of undifferentiated fever." (PMID 29284474, 2017). "As well as a dengue RDT, they had also modeled cost-effectiveness of a scrub typhus RDT and CRP test." (PMID 29284474, 2017). "The current retrospective study also looked at C-reactive protein (CRP) and its differences between the dengue and the OFI group." (PMID 29098002, 2017). "Percentage of patients with each infection that would receive an antibiotic using either a dengue RDT, a scrub typhus RDT or CRP RDT with a threshold of 20mg/L, as compared with current practice." (PMID 27027303, 2016). "We aimed to evaluate the utility of C-reactive protein (CRP) levels for distinguishing between mild and severe cases in the early phase of the dengue illness." (PMID 26247033, 2015). "Our study highlights the utility of the CRP levels in early prediction of DSS and severe dengue in adult patients." (PMID 26247033, 2015). "The difference in the cutoff level of CRP for DSS and severe dengue can be explained by the different classification schemes for detecting severe cases of dengue." (PMID 26247033, 2015). "All patients were subjected to TC, CRP, PCT, IgM Dengue, IgM Chikungunya, pus and blood culture and sensitivity." (PMID 23826894, 2013). "Hence, we mapped this study to evaluate and compare various clinical parameters (i.e., CBC, platelet count, IPF, liver and kidney function tests, CRP, serum lactate dehydrogenase (LDH), and ferritin levels) of the dengue patients." (PMID 40109796, 2025).
dengue (continued). "The proinflammatory markers IL-6 and CRP were elevated in patients with anti-SARS-CoV-2 and dengue IgG antibodies compared with those with only anti-dengue IgG antibodies, highlighting the potential role of anti-SARS-CoV-2 antibodies as cross-reactive antibodies." (PMID 41583452, 2025). "Area under curves and the 95% CI were excellent for discriminating leptospirosis from dengue fever and no significant statistical difference was found between the AUC for the final model and the CRP alone model (DeLong test, p = 0.146)." (PMID 37195992, 2023). "‘...if no source of infection is identified in the patient and their CRP values are not high, it must be a case of dengue fever and not a bacterial infection.’ – Resident in paediatrics, 7 years experience." (PMID 36732718, 2023). "Studies have shown higher levels of C-reactive protein (CRP) in severe dengue versus non-severe dengue, with a CRP cutoff level of 30.1 mg/L (AUC, 0.938; 100% sensitivity, 76.3% specificity)." (PMID 32063229, 2020). "CRP was positive in 8 of 24 tested cases (33.3%): the highest value (189 mg/dL) was registered in the case of severe dengue, where no bacterial superinfection was demonstrated." (PMID 33158274, 2020). "When compared to patients with nonsevere dengue, patients with severe dengue had significantly higher CRP levels (P = 0.009)." (PMID 26247033, 2015). "According to the 2009 WHO dengue severity classification, the median CRP level was significantly higher for severe dengue compared to nonsevere dengue during the febrile phase (36.2 mg/L versus 14.4 mg/L; P = 0.025)." (PMID 26247033, 2015). "Greater levels of CRP have been observed among dengue patients compared with age-matched non-dengue controls and among those with greater dengue severity." (PMID 24168271, 2013). "Nevertheless, the use of the CRP, and maybe, the use of CRP RDT, can also help to differentiate dengue from bacterial infection." (PMID 24069477, 2013). "It is essential to understand the reasons why CRP and dengue RDTs, for example, are not used as widely as would be expected and why variations in uptake between settings exist, because these may also be applicable to any multiplex LF-RDTs developed." (PMID 36367878, 2022). "However, our results highlight the risk of inadvertently increasing inappropriate antibiotic prescribing if dengue is not first considered in patients with CRP > 20 mg/L during seasons of high incidence." (PMID 32063229, 2020). "However, there has not been a study evaluating the use of CRP levels to distinguish between mild and severe dengue during the early phase of infection." (PMID 26247033, 2015). "Among 428 dengue patients with CRP level at enrollment of > 40 mg/L and without clinically suspected bacterial infection, 417 (97%) patients did not receive antibiotics (12 from severe dengue group, 107 from intermediate dengue group, and 298 from uncomplicated dengue group)." (PMID 32063229, 2020). "Although a preliminary diagnosis of severe dengue was first entertained, dengue serology produced negative results, and the levels of antistreptolysin O titer (ASO) and C-reactive protein (CRP) were within normal ranges." (PMID 39161486, 2024). "The levels of CRP, SAA, sVCAM-1 and sICAM-1 were similar in dengue patients with or without hemorrhagic manifestations." (PMID 38235130, 2023). "Four eligible biomarkers, CRP, TNF-α, IL-10, and IFN-γ, found no significant variation in marker levels when comparing severe and non-severe dengue." (PMID 34610027, 2021). "Factor H was also highly correlated with platelet levels in the dengue patients, whereas C1q, CIC-C1q, CRP, and MBL protein levels were not." (PMID 19707565, 2009). "The levels of CRP (p < 0.0001), SAP (p < 0.0001), ferritin (p < 0.0001), TNF-α (p < 0.0001) and IL-1β (p < 0.0001) were high in patients with Severe Dengue as compared to Dengue without warning signs." (PMID 33436908, 2021).
dengue (continued). "In our study, median CRP level was significantly higher in those with nonshock DHF versus DF, DSS versus DF, DSS versus nonshock DHF, DSS versus DF/nonshock DHF, and severe dengue versus nonsevere dengue." (PMID 26247033, 2015). "Interestingly, the level of CRP was shown to be relatively low in DF and nonsevere dengue patients (median CRP < 10 mg/L), whereas extremely high CRP level was found in patients with DSS (median CRP > 100 mg/L) and severe dengue (median CRP > 30 mg/L)." (PMID 26247033, 2015).
sleep disorder (84 papers, 2009 to 2026). A change from the patient's baseline sleeping pattern, in the hours slept and/or an alteration/dysfunction in the stages of sleep. "Inflammatory markers, such as C-reactive protein (CRP) and interleukin-6 (IL-6), are closely associated with sleep disorders." (PMID 40894321, 2025). "Mechanistically, sleep disorders are known to promote systemic inflammation, elevating levels of C-reactive protein and interleukin-6, which are associated with increased mortality risk." (PMID 40290660, 2025). "We found interesting phenomena, particularly that younger individuals and those with lower BMI or higher CRP levels are especially susceptible to the adverse effects of sleep disorders on kidney function." (PMID 41340851, 2025). "Based on previous studies showing that Vitamin C reduced the inflammatory response, which has been associated with sleep disorders, we chose C-reactive protein (CRP), a classic indicator of the inflammatory response, to conduct the mediation analysis." (PMID 39519494, 2024). "Some models also incorporate reversible predictors such as C-reactive protein, albumin, calcium, and parathyroid hormone to forecast the risk of sleep disorders." (PMID 39408273, 2024). "A recent meta-analysis demonstrated that sleep disturbances are associated with higher levels of CRP and IL−6, which also represent the most consistently identified immunologic abnormalities in MDD." (PMID 37176140, 2023). "Multiple studies in individuals with MDD have demonstrated that sleep disturbances were associated with higher levels of circulating C-reactive protein (CRP), serum tumour necrosis factor (TNF) α, interleukin(IL)−6, interferon(IFN)-α2, and IFN-γ." (PMID 37176140, 2023). "Peer victimization predicted increased inflammatory responses to social stressors in vulnerable adults, and higher levels of C-reactive protein were associated with sleep disturbances." (PMID 37181869, 2023). "The mechanism behind the development of sleep disorders was associated with the release of cytokines like TNFα, IL-6 and C-reactive protein (CRP)." (PMID 36560927, 2022). "It seems that sleep disorders are associated with an increase in body inflammation, expressed by an increase in C-Reactive Protein (CRP) and Interleukin-6 (Il-6) concentration." (PMID 33153051, 2020). "Although this study is the first to evaluate the association between sleep quality and CRP in a large population, earlier experimental studies on the impact of sleep restriction and sleep disorders on inflammatory and immunologic parameters have been reported." (PMID 24663098, 2014). "Each sleep disorder was significantly associated with increased hs_CRP and correlative to other sleep disorders." (PMID 24663098, 2014). "Additionally, sleep disorders were significantly associated with low eGFR in those aged <60 years and CRP ≥1.8 mg/L." (PMID 41340851, 2025). "In addition, sleep disturbances and cognitive dysfunction are independently associated with increased inflammatory markers such as c-reactive protein (CRP) and interleukin-6 (IL-6)." (PMID 40898257, 2025). "For example, sleep disturbances are associated with higher levels of C-reactive protein (CRP) and interleukin-6 (IL-6), which are also commonly elevated in musculoskeletal and neuropsychiatric diseases, and among people with a fast accumulation of chronic diseases." (PMID 33280611, 2020). "Furthermore, two population-based studies found that consumption of red and processed meat has been associated with circulating inflammation markers, including C-reactive protein and interleukin-6, which have been linked to sleep disorders." (PMID 31011478, 2019). "Furthermore, sleep disorders may exacerbate chronic inflammation in the gallbladder, with elevated inflammatory markers such as interleukin-6 (IL-6) and C-reactive protein (CRP) being associated with increased gallstone risk." (PMID 40313242, 2025).